FGF21 (fibroblast growth factor 21)
Diseases named in the same sentence as FGF21 in open-access papers (continued):
Sharing a sentence is not in itself a finding about the gene and the disease.
Obesity (continued). "FGF21 has the potential to activate glucose uptake in adipocytes, being also studied in mice models to show its role in the inflammatory state of obesity." (PMID 34019585, 2021). "The inflammatory presence effectively leads to higher FGF21 production and a further imbalance of nutritional regulation, thus closing the vicious circle of obesity." (PMID 34578793, 2021). "As non-coding microRNAs are post-transcriptional regulators of genes translation, we analysed the microRNA profile in patients with obesity and high FGF21 levels." (PMID 33670024, 2021). "A clinical study found human BMI were positively correlated with their circulating FGF21 concentrations, and the increased FGF21 concentrations compensate for the insulin resistance induced by obesity and other factors." (PMID 34912302, 2021). "Our studies suggest that reversal of blood glucose, body weight, and fat mass in established obesity, IR, and hepatic steatosis is, in large part, attributable to Fgf21 in Tg-rtTA mice." (PMID 34023388, 2021). "Adding to the complex relationship between obesity and increased FGF21, it has been recently shown that UCP1-KO mice, which are resistant to diet-induced obesity at ambient 230C, displayed a 2.5-fold increase in serum FGF21 levels when fed a HFD." (PMID 35046901, 2021). "introduced the notion that FGF21 is a critical player in the expansion of subcutaneous fat required for obesity." (PMID 35046901, 2021). "In this section, we highlight fasting and obesity as two ends of the nutritional spectrum with a focus what is known about the role of skeletal muscle-derived FGF21." (PMID 33762965, 2021). "Studies indicate that circulating levels of FGF21 are elevated in several metabolic diseases, such as obesity, type 2 diabetes, and fatty liver disease." (PMID 33762965, 2021). "FGF-21 is released from the liver and participates in the glucose and lipid metabolism, having a protective role against obesity, diabetes, and NAFLD." (PMID 33924457, 2021). "This point is of relevance when considering a possible FGF21 resistance or insulin resistance in obesity and T2D." (PMID 33805553, 2021). "It should also be taken into account, that findings in mice suggested development of FGF-21 resistance in obesity." (PMID 33805553, 2021). "For FGF21, protein levels were slightly higher in the overweight/obesity groups in both patients and controls." (PMID 34019585, 2021). "Studies have reported that FGF21 is increased in patients with non-alcoholic fatty liver disease, obesity, and diabetes." (PMID 34513950, 2021). "Serum level of circulating FGF21 increases with age as well as in obesity and insulin resistance state." (PMID 33670024, 2021). "These agents are centered on the ability of FGF21 to increase glucose uptake and reduce body weight, which is essential for treating obesity and diabetes." (PMID 34572066, 2021). "Elevated blood FGF21 levels have been also observed in human subjects suffering from obesity, type 2 diabetes mellitus (T2DM) and fatty liver, likely as a result of increased NEFA concentrations in blood and ER stress induction in the liver." (PMID 34517929, 2021). "Hepatic Fgf21 expression is increased in the patients with hepatic steatosis, in mouse models of obesity or nonalcoholic fatty liver disease, and in response to ER stress." (PMID 34129049, 2021). "The results in our study also demonstrated a significant correlation between FGF21 levels and obesity, BMI, body surface area, total cholesterol and LDL cholesterol." (PMID 34573919, 2021). "A recent study showed that mice lacking Drp1 in the liver exhibited increased energy expenditure and protected against HFD‐induced obesity due to elevated expression of FGF21." (PMID 33904649, 2021). "Paradoxically, serum levels of FGF21 are increased in individuals with obesity, type 2 diabetes, and metabolic syndrome." (PMID 34799626, 2021).
Obesity (continued). "As a novel fibroblast growth factor (FGF) family member identified in 2000, FGF21, has emerged as an important regulator and orchestrator of glucose and lipid metabolism and energy homeostasis with the potential to treat obesity, T2DM, and meta-inflammation." (PMID 34680216, 2021). "In Chinese children with obesity, high FGF21 serum levels correlated inversely with adiponectin levels implicating a potential FGF21 resistance in obese states, since FGF21 treatment of mice results in increased adiponectin secretion." (PMID 33805553, 2021). "After birth, the methylation status of fibroblast growth factor-21 (fibroblast growth factor-21 gene) can persist into adulthood and affect the obesity rate in adulthood." (PMID 34034810, 2021). "To identify potential downstream factors of betaine-altered gut microbiota in reducing obesity, we measured Fgf21 in both WAT and hepatic tissues, the two main producers of Fgf21." (PMID 33550882, 2021). "The UCP1/FGF21 dKO mouse unambiguously pinpoints endogenous FGF21 as primary crucial mediator of obesity resistance, and iWAT as the target organ." (PMID 32005798, 2020). "Insufficient expression of hepatic fibroblast growth factor 21 (FGF21) and stromal cell-derived factor 2 like 1 (Sdf2l1) reportedly leads to insulin resistance and hepatosteatosis in obesity and type 2 diabetes." (PMID 32978487, 2020). "This conclusion was reached based on some observations that circulating FGF21 levels are increased in obesity, with lower FGF21 receptor expression levels on target tissues such as adipose tissue." (PMID 32158768, 2020). "Circulating FGF21 levels are elevated in NAFLD patients, suggestive of FGF21 resistance in obesity and defective autophagy has been implicated in the development and pathogenesis of NAFLD5,6,31." (PMID 32042044, 2020). "FGF21 is a key regulator of energy balance and metabolism in mammals, and has emerged as a therapeutic potential for treating obesity and diabetes." (PMID 32332781, 2020). "FGF21 or GDF15 increased skeletal muscle expression play protective roles against diet-induced obesity and insulin resistance." (PMID 33374852, 2020). "In the liver, FGF21 regulates hepatic glucose production and fatty acid oxidation and prevents diet-induced obesity and hepatic steatosis." (PMID 32366854, 2020). "It was previously shown that systemic administration of FGF21 has therapeutic benefits against obesity-related medical complications in obese animals." (PMID 32546231, 2020). "We reported previously that metformin improves obesity and metabolic dysfunction by activating fibroblast growth factor 21 and regulating Th17/Treg imbalance." (PMID 32276645, 2020). "The regulator of this process, Fgf21, was also identified as a hub gene in obesity-induced cardiac tissue." (PMID 32610475, 2020). "There results suggest the potential of FGF21 as a drug candidate to treat obesity-related type 2 diabetes." (PMID 32225108, 2020). "Acute exercise increases irisin and FGF-21, although this is dependent on the intensity of exercise, whereas obesity has the opposite effect." (PMID 32230849, 2020). "In a study of the inhibitory effect of FGF21 on diabetes mellitus, it was found that autophagic damage in cells induced expression of FGF21, thereby inhibiting obesity and insulin resistance‐induced diabetes." (PMID 32233059, 2020). "Surprisingly, some of our newest data highlight mild cold-induced endogenous FGF21 as the primary metabolic regulator of obesity resistance, possibly mediated via WAT browning in UCP1-KO mice." (PMID 32714278, 2020). "It has been demonstrated that FGF21 has the potentiality to reduce the effects of obesity on pancreatic carcinogenesis." (PMID 32411709, 2020). "Our findings strongly suggest that DT holds nutraceutical potential for the prevention of obesity and metabolic diseases by regulating adipose tissue functions including stimulation of brown fat formation via FGF21 production." (PMID 32516922, 2020).
Obesity (continued). "Fibroblast growth factor 21 (FGF21) is an endocrine regulator of lipid metabolism and energy homeostasis that has shown promise as a therapeutic against obesity and type 2 diabetes." (PMID 32350364, 2020). "Fisher F.M., Chui P.C., Antonellis P.J., Bina H.A., Kharitonenkov A.,Flier J.S., Maratos-Flier E. Obesity is a fibroblast growth factor 21(FGF21)-resistant state." (PMID 35087997, 2020). "Obesity has been described as an FGF21-resistant state because elevated circulating levels of FGF21 and attenuating FGF21 signaling responses with an impaired reduction in circulating glucose and lipid were observed in diet-induced obese mice." (PMID 32210348, 2020). "Coskun T., Bina H.A., Schneider M.A., Dunbar J.D., Hu C.C., Chen Y.,Moller D.E., Kharitonenkov A. Fibroblast growth factor 21 corrects obesity in mice." (PMID 35087997, 2020). "FGF21 analogs are being pursued as drug candidates for treating T2D as well as obesity and nonalcoholic steatohepatitis, and emerging human clinical trial data appears promising." (PMID 32923621, 2020). "Its efficacy in humans promoted the interest in FGF21 as a promising therapeutic molecule for various metabolic diseases (e.g., obesity, type 2 diabetes, and non-alcoholic fatty liver disease)." (PMID 32714278, 2020). "Obesity increases expression of FGF21, KLB, FGFR1c, and FGFR3c in the liver, although FGFR2c remains the most highly expressed of FGF21’s receptors in the liver." (PMID 33381084, 2020). "Here we identify the enigmatic factor as endogenous FGF21, which is primarily mediating obesity resistance." (PMID 32005798, 2020). "Although FGF21 has several beneficial effects for glucose and lipid metabolism, circulating FGF21 levels are paradoxically increased in hepatosteatosis, obesity, and type 2 diabetes." (PMID 32978487, 2020). "Future studies are necessary to continue determining the role of magnitude effects of FGF21 levels in obesity to improve clinical practice, especially in paediatrics population." (PMID 32267352, 2020). "Recently, it has been investigated the role of a metabolic regulator that prevents obesity, fibroblast growth factor 21 (FGF21), in KRAS oncogenic context of pancreatic cancer." (PMID 32411709, 2020). "FGF21 is a hormone-like cytokine known to play key roles in glucose and lipid metabolism and it is currently being pursued as a therapeutic drug for obesity and T2-diabetes." (PMID 32397676, 2020). "This is the first report showing the effects of DT on FGF21 production, brown fat formation, and inhibition of diet-induced obesity." (PMID 32516922, 2020). "People with obesity have elevated blood levels of FGF21 but also develop resistance to its action, impairing its beneficial action." (PMID 32267352, 2020). "Markan suggests that the role in increased circulating FGF21 during obesity remains uncertain and the translating rodent studies to man needs to be done with caution." (PMID 32267352, 2020). "FGF21 exerts beneficial effects on obesity and related metabolic diseases via multiple actions, such as enhancements of insulin-mediated glucose uptake and β-oxidation/thermogenesis, as well as amelioration of ER stress." (PMID 32225108, 2020). "Pharmacological application of FGF21 holds great promise as an effective therapeutic means for treating obesity and diabetes 11-13." (PMID 32929325, 2020). "Conversely, FGF21 gene knockout mice fed a ketogenic diet exhibited mild obesity and increased hepatic fat accumulation." (PMID 32957703, 2020). "The aim of the present investigation was to assess the individual variability of FGF21 concentration and its impact on BC in adolescents with obesity undergoing long-term interdisciplinary WL therapy." (PMID 32267352, 2020). "It appears that miR-34a expression is elevated in obesity in part through suppression of the browning activators fibroblast growth factor 21 (FGF21) and SIRT1 to inhibit fat browning." (PMID 32646451, 2020).
Obesity (continued). "Fibroblast Growth Factor 21 (FGF21) is assumed to beone of the most promising candidates for obesity treatment,because administration of FGF21 or its analogs was shownto reduce body weight in laboratory rodents, monkeys, andhumans." (PMID 33659800, 2020). "Future studies are necessary to continue determining the role of FGF21 levels in obesity to improve clinical practice, especially in paediatrics population." (PMID 32267352, 2020). "Recent evidence indicates that the anti-obesity and anti-diabetic activities of FGF21 are UCP1-independent." (PMID 32849287, 2020). "In humans, circulatory levels of FGF21 increase with obesity and reflect the increased accumulation of lipids." (PMID 32570721, 2020). "Expectedly, like FGF21, patients with obesity-related insulin resistance present increased basal levels of follistatin, but its exercise-induced release by the liver is blunted." (PMID 32604889, 2020). "The objective of this study was to investigate the pharmacologicaleffects of FGF21 in male and female mice withmelanocortin obesity." (PMID 33659800, 2020). "FGF21’s ability to reduce body weight, glucose levels, and lipid concentrations in models of obesity generated substantial initial interest." (PMID 32047920, 2020). "FGF21 directly acts in the brain to increase the insulin sensitivity and metabolic rate in rats with diet-induced obesity." (PMID 32724479, 2020). "Overall, in the current study, we indicate that exaggerated fasting and postprandial GIP secretion in obesity is associated with elevated ALT, GGT, FLI, as well as FGF-21 plasma levels." (PMID 32069846, 2020). "Obesity increased body weight, which was unaffected by exercise training and decreased plasma irisin and FGF-21." (PMID 32230849, 2020). "Not much is known about these cytokines in relation to obesity or HDL, apart from for FGF19 which, like its related hormone FGF21 mentioned earlier, is being investigated as a pharmacological target for obesity." (PMID 33204460, 2020). "Among all neurotrophic factors, brain-derived neurotrophic factor (BDNF) and fibroblast growth factor 21 (FGF21) are most relevant to obesity, T2DM, and metabolic diseases." (PMID 32210348, 2020). "FGF-21 has multiple metabolic actions in animal models of obesity that include enhancing insulin sensitivity, decreasing triglyceride concentrations, and causing weight loss." (PMID 32069846, 2020). "While mild cold is required as the trigger of FGF21 release, this hormone fully unfolds its anti-obesity effects under high-fat diet conditions." (PMID 32005798, 2020). "FGF21 treatment alleviated the fatty liver disease in a mouse model of obesity in line with its actions on hepatic lipid oxidation and lipolysis in white adipose tissue (WAT)." (PMID 32957703, 2020). "Regarding circulating serum FGF21, its concentration was higher in db/db control group as a result of FGF21 resistance in obesity and diabetes." (PMID 32784488, 2020). "The direct relationship between BAT and muscle mass in this population of adolescents it has been elucidated, while high FGF21 levels observed in adolescents with obesity were positively correlated with liver and visceral fat levels." (PMID 32267352, 2020). "People with obesity have elevated blood levels of FGF21, but also develop resistance to its action, impairing its beneficial role." (PMID 32267352, 2020). "Strikingly, we discover that endogenous fibroblast growth factor 21 (FGF21) is the single key regulator mediating paradoxical resistance to obesity." (PMID 32005798, 2020). "We found a regulation of IL-6, IL-8, IL-15, IL-18, and FGF21 in plasma by exercise, while obesity status increased IL-13 and decreased IL-8 and SPARC in the circulation." (PMID 32132925, 2020). "On the other hand, our previous and present results demonstrated that despite obesity and hyperglycemia, plasma FGF21 levels were decreased in young (6-week-old) and old (9-week-old) db/db mice compared with C57BL6J mice fed a chow diet." (PMID 33364514, 2020).
Obesity (continued). "We saw in the immunometabolism component that obesity and known related clinical variables associated with elevated levels of cytokines TRANCE, CCL4, IL18R1, CCL3 and FGF21, for which known links to obesity were discussed." (PMID 33204460, 2020). "It is clear that FGF21 levels become elevated as obesity develops in mice and humans, and are positively correlated with BMI, adiposity, and FGF21 expression levels in adipose tissue." (PMID 32158768, 2020). "Here, we observed significant alterations in Gck and Fgf21 expression, indicating a severely disturbed glycolysis metabolism in the myocardium, which was stimulated by obesity." (PMID 32610475, 2020). "Despite the potential beneficial effects of FGF21, increased endogenous FGF21 levels have been observed in adults with obesity." (PMID 32546231, 2020). "Transgenic mice overexpressing FGF21 in the liver are protected against diet-induced obesity, and FGF21 pharmacotherapy in diabetic and obese mice rapidly improves metabolic abnormalities." (PMID 31312114, 2019). "Previous studies have shown that endogenous levels of FGF21 increase in genetically and/or diet-induced obese mice, and the exogenous FGF21 response is severely impaired in the obese mice, suggesting that obesity is a state of FGF21 resistance." (PMID 31312114, 2019). "Obesity is considered an FGF21-resistant state usually due to a downregulation of the fibroblast growth factor receptor (FGFR) and/or its co-receptor β-klotho (KLB) that impairs FGF21 signaling." (PMID 31480627, 2019). "FGF21 functions as an endocrine hormone with anti-inflammatory, anti-diabetic, and anti-obesity effects and is produced in peripheral tissues (e.g., liver, white and brown adipose tissues, skeletal muscle, and pancreas)." (PMID 31312114, 2019). "As FGF21 has been shown to reduce glucose and lipid levels, it has been suggested as a potential therapeutic agent for the treatment of diabetes, obesity, and dyslipidemia." (PMID 30927227, 2019). "There is a paradoxically positive correlation with elevated serum FGF21 levels and metabolic disorders like obesity, diabetes, mitochondrial diseases, and aging." (PMID 31057418, 2019). "Circulating FGF21 levels are elevated in subjects with obesity, T2D, and MetS, and positively correlate with triglycerides, fasting insulin, and insulin resistance." (PMID 31736870, 2019). "FGF21 is considered an anti-obesity hormone, which circulates at variable levels and plays a role in mediating the physiological response to metabolic changes." (PMID 31546675, 2019). "Some studies link the excess of fatty acid in obesity and type 2 diabetes with the overexpression of the FGF21 detected in these individuals." (PMID 31546675, 2019). "In various rodent models of diet-induced obesity a positive correlation between the beneficial effects of polyphenol-rich fruit extracts and FGF21 has been described." (PMID 31480627, 2019). "Serum FGF21 levels were significantly higher in obesity and type 2 diabetes mellitus (T2DM) populations." (PMID 31582974, 2019). "FGF21 analogues have progressed to the point of being investigated in multiple human trials for the indications of obesity, diabetes, and other metabolic disorders." (PMID 31370146, 2019). "This study aimed to evaluate the feasibility of combining FGF-21, obesity indices, and biochemical tests for predicting high-grade liver steatosis in children." (PMID 31750276, 2019). "It has been widely described that FGF21 levels are increased in obesity and diabetes in both animal models and humans." (PMID 31480627, 2019). "In this sense, it has been demonstrated that FGF21 stimulate lipid disposal and thermogenesis in brown adipose tissue in obesity, while it increases lipoprotein disposal into white adipose tissues in lean mice." (PMID 31405194, 2019). "The discovery of the FGFs (FGF19, FGF21) and their influences on the body energy balance as hormones demonstrate significant progress in obesity and type 2 diabetes studies." (PMID 31151464, 2019).